TIGIT (T cell immunoreceptor with Ig and ITIM domains)
Diseases named in the same sentence as TIGIT in open-access papers (continued):
Sharing a sentence is not in itself a finding about the gene and the disease.
tumor (continued). "Furthermore, the effector function of TIGIT+CD8+ tumour‐infiltrating lymphocytes (TILs) was impaired in LUAD patients and TIGIT inhibited antitumour immune response of CD8+ TILs in tumour‐bearing mice." (PMID 38279870, 2024). "Tiragolumab is a fully human IgG1/kappa anti-TIGIT monoclonal antibody with an intact Fc region that prevents the binding of TIGIT to PVR that is well tolerated and has demonstrated promising anti-tumor activity in combination with the PD-L1-inhibitor atezolizumab in phase I and II clinical trials." (PMID 38206370, 2024). "The CD155/TIGIT axis is essential to support immune evasion; when combined with PD-1 blockade plus CD40 activation, the CD155/TIGIT targeting stimulates a robust anti-tumor response in preclinical models of PDAC." (PMID 38817612, 2024). "It is consistent with the view that TIM-3 functions as a co-inhibitory immune checkpoint molecule in AML on NK cells, similar to the role of PD-1 and TIGIT in previous studies, and coincides with the reports of the role of TIM-3 expression on NK cells in other tumor types." (PMID 39767624, 2024). "TIGIT was highly expressed in HCC and increased with tumor differentiation." (PMID 37124530, 2023). "ICs were upregulated on stromal immune cells within the tumour including PD-L2, CTLA-4 and TIGIT." (PMID 36445478, 2023). "TIGIT is highly expressed on tumor-infiltrating lymphocytes (TIL) in several hematological malignancies including follicular lymphoma, CLL, classic HL, AML, and relapsed MM, helping in tumor progression and poor outcome." (PMID 37569880, 2023). "If overactivated, the TIGIT pathway leads to an abnormal intracellular transduction of suppressive stimuli in T and NK cells, thus facilitating neoplastic cell survival in CD155+ neoplasms, such as CLL and RS." (PMID 36831361, 2023). "In the untreated tumor, half of all T cells belonged to the exhausted CD8+ T cell cluster, characterized by expression of residence and checkpoint molecules such as PD-1, TIGIT, CTLA-4, LAG-3, CD69, and CD103." (PMID 37209684, 2023). "As clinically effective antibodies against TIGIT and TIM-3 are currently tested in trials, these ICI might deserve investigation in this neoplastic disease along with TT." (PMID 37048617, 2023). "Our study showed that NK cell inhibitory receptors such as TIGIT, LAG3 and TIM-3 were all upregulated and that exhaustion of NK cell may induce immune escape and tumor progression in NK-NPC." (PMID 37098551, 2023). "Only the expression of TIGIT and CTLA-4 increased in both subsets at the tumor site." (PMID 37898752, 2023). "Hence, we confirmed the presence of Vδ2− cells co-expressing PD-1, TIGIT and TIM3, which overall represented about 8% of tumor-infiltrating Vδ2− cells and which were enriched in tumor versus healthy kidney samples." (PMID 36928415, 2023). "While targeting other potential immune checkpoints, small molecules or antibodies that disrupt negative regulation between tumor cells and T cells or between bone marrow cells and T cells, such as LAG3, TIGIT, TIM3, B7H3, CD39, CD73, and Adenosine A2A receptors, are in clinical trials." (PMID 38003338, 2023). "Treatment with the mIgG1 backbone anti-TIGIT mAb did not drive antitumor activity in the CT26 syngeneic murine tumor model, despite showing robust ability to block the inhibitory TIGIT signaling axis." (PMID 38022590, 2023). "Additionally, a strong correlation between RHBDF2 upregulation and immune checkpoint genes (PDCD1, CD274, LAG3, CTLA4, TIGIT, HAVCR2) was observed in HCC, and these immune checkpoint genes can contribute to tumor immune escape and promote tumor progression." (PMID 36943228, 2023).
tumor (continued). "TIGIT interacts with several ligands, including CD155, expressed on some tumor cells." (PMID 37175653, 2023). "We previously observed such an engagement of the complement system following treatment of the same tumor model with NBTXR3+XRT in tandem with checkpoint inhibitors of PD1, LAG3, and TIGIT — a treatment combination that yielded similarly impressive results to the therapy in this study." (PMID 37345658, 2023). "In addition, we examined the expression levels of PD1, PDL1, CTLA4, TGFB1, TIGIT, IDO1, and LAG3 in 51 tumor samples." (PMID 37928532, 2023). "However, it was found that CAC exhibited a significantly enriched presence of TIGIT (p = 0.011) and TOX (p < 0.0001) in comparison to the corresponding tumor-free mucosa." (PMID 37835436, 2023). "In response to restimulation with the tumor-specific peptide, induction of the CD8+ T cell effector cytokine interferon gamma (IFN-γ) was greatly enhanced from splenocytes of CT26-bearing mice treated with an anti-TIGIT antibody with an intact Fc backbone." (PMID 38022590, 2023). "TIGIT could be engaged with the two ligands, CD155 (PVR) and CD112 (PVRL2, Nectin-2), expressed by tumor cells and antigen-presenting cells in the tumor microenvironment." (PMID 38203670, 2023). "Moreover, we observed proliferation of T cells featuring Ki67 expression and enhanced anti‐tumor immunity featuring perforin and IFNG upregulation within the TIME after ICB treatment, especially in the anti‐TIGIT group." (PMID 36725337, 2023). "Thus, full restoration of DNAM-1 signalling, and optimal anti-tumour CD8+ T cell responses, requires blockade of TIGIT and PD-1, providing a biological rationale for combinatorial targeting in the clinic." (PMID 37325585, 2023). "Additionally, highly suppressive TIGIT+ Tregs were associated with a profound anti-tumor response, and some researchers hypothesize that the deprivation of TIGIT on Tregs, not on CD8+ TILs, enhances the anti-tumor response by reestablishing the cytotoxic properties of CD8+ T cells." (PMID 36980196, 2023). "In addition to using mAbs to block ICPs expression and restore tumor-infiltrating immune cell function, several approaches for targeting LAG-3, TIM-3, and TIGIT via immunotherapy, such as the development of BsAbs, have been reported." (PMID 37670328, 2023). "The presence of CD8+ T cells expressing inhibitory markers such as LAG3, TIGIT, KLRC1, and PD-1, and FOXP3+ regulatory CD4+ T cells may prevent effective T cell–mediated tumor control in PDAC." (PMID 37751306, 2023). "Binding of vitamin D to VDR resulted in decreased expression of immune checkpoint inhibitors (PD-1, TIGIT, and Tim-3) and increased expression of the co-stimulatory molecule CD28 on CD8+ T cells, which increased their cytokine production and anti-tumor activity." (PMID 37175993, 2023). "TIGIT (T cell immunoglobulin and ITIM domain), also named as WUCAM, Vstm3, and VSIG9, has been reported to possess the ability of suppressing both T cell-driven inflammation and T cell and NK cell-dependent anti-tumor immunity, as a coinhibitory receptor and a novel immune checkpoint." (PMID 36765782, 2023). "The results from preclinical tumor models presented that therapeutic targeting of CD96 and TIGIT has demonstrated significant efficacy and synergistic activity with PD-1 inhibition, which could restore T cell exhaustion to a certain extent." (PMID 37312116, 2023). "TIGIT (T-cell immunoreceptor with IgG and ITIM domains), whose expression is inhibited by IFNs80, was recently identified as a cancer stem cell marker in LUAD81 and TIGIT expression on tumor cells was shown to supress CD8 T cells and NK cells." (PMID 37258521, 2023). "As a dual blockade of the PD-1/TIGIT ICPs, ZG005 showed sustained occupancy of both targets and was able to specifically inhibit their pathways simultaneously, resulting in synergistic effects and enhanced ability of the immune system to kill tumor cells." (PMID 37670328, 2023).
tumor (continued). "Moreover, the blockade of TIGIT and PD-1 can help restore the CD226 signaling on CD8+TILs and optimize the CD8+T cell-mediated anti-tumor response." (PMID 37056782, 2023). "We found that anti-TIGIT therapy alone had no statistically significant impact on tumor growth (except for the B16 F10 model), whereas RT alone slowed tumor progression." (PMID 35794399, 2023). "These tumor-resident Vδ2− T cells can express the transcriptional program of exhausted αβ CD8+ T cells as well as canonical markers of terminal T-cell exhaustion including PD-1, TIGIT and TIM-3." (PMID 36928415, 2023). "Also, it is surprising that the specific knockout of the TIGIT gene in NK cells can reverse the depletion of NK cells and significantly reduce the expression of PD1 in tumor-infiltrating cytotoxic T cells." (PMID 37035135, 2023). "We focused on TIGIT and CD155 expression on tumor and effector cells." (PMID 37444427, 2023). "The improved activity correlated with the biased FcγR interaction profile of the nonfucosylated anti-TIGIT mAb, which supports that FcγRIIIa binding with decreased FcγRIIb binding favorably activates APCs and enhances tumor-specific CD8+ T cell responses." (PMID 38022590, 2023). "In the process of APOBEC mutagenesis, the increased expression of important immune checkpoint molecules, including PDCD1, TIGIT, HAVCR2, LAG3 and IDO1, and the elevated CYT score, which serves as cytotoxic effects and anti-tumor response, were highly suggestive of better immunotherapy response." (PMID 37215984, 2023). "Neutralizing TIGIT with anti-TIGIT antibodies has resulted in the partial recoveries of IFNγ and IL-17 expression by CD4+ T cells, suggesting it is a considerable marker to reactivate the immune system against tumor development." (PMID 37046842, 2023). "Taken together, these data suggest that TIGIT+ NK cells represent a more activated cell subpopulation of NK cells with greater anti-tumor response capacity, and those cells are not inherently exhausted." (PMID 37345049, 2023). "In Ccl21a-KO tumor, the intratumoral Tregs showed lower co-inhibitory receptors TIM-3 and TIGIT." (PMID 37664721, 2023). "Nevertheless, the expression of exhaustion-associated proteins in tumor-infiltrating CD8+ T cells — including immunosuppressive receptors PD-1, TIM-3, TIGIT, and LAG3 — were not affected by Rig-I deficiency." (PMID 36927693, 2023). "We found that the anti-α-TIGIT scFvs expression and secretion could interrupt the interaction of TIGIT with its ligand CD155, therefore enhanced CAR T cells infiltration and activation to promote tumor regression in vivo." (PMID 37359558, 2023). "In the BATF3−/− mouse model, the anti-tumor effect of RT plus anti-TIGIT combination therapy was absent." (PMID 35794399, 2023). "ICB therapy is an emerging immunotherapy aiming at blocking immunosuppressive tumor signals and restoring anti-tumor immune responses by targeting checkpoint receptors or ligands such as PD-1/PD-L1, CTLA-4, TIGIT, LAG-3, TIM3, among which PD-1/PD-L1 is the most common research object." (PMID 38283361, 2023). "This proved to be particularly true for a subset of tumor-infiltrating Vδ2− cells identified in our analysis, which we designated PTT+ owing to their co-expression of established markers of αβ T-cell exhaustion, PD-1, TIGIT and TIM-3." (PMID 36928415, 2023). "A blocking antibody against TIGIT, an inhibitory receptor on NK cells bearing ITIM- and Ig tail-tyrosine (ITT)-like motif, can reverse the exhausted phenotype of TIGIT-upregulated tumor-infiltrated NK cells, constrain tumor growth, and improve the survival tumor-bearing mice in vivo." (PMID 37638058, 2023). "A great range of immune checkpoint molecules, such as PD-1, PD-L1, CD73, Lag-3, B7-H3, TIM-3, CTLA-4, TIGIT, and VISTA in the tumor microenvironment (TME) are involved in important mechanisms that prevent effector T cells’ anti-tumor activities." (PMID 37008041, 2023).
tumor (continued). "Furthermore, distinct cancer types were shown to inhibit glucose uptake and effector function by inducing TIGIT expression in CD8+ T cells, resulting in an impaired anti-tumor immunity." (PMID 36874131, 2023). "TIGIT blockade during co-culture with A549 spheroids did not mitigate the tumor-induced decrease in IFNγ expression after restimulation with PVR− cells with still only 9 ± 7% of cells expressing IFNγ." (PMID 37345049, 2023). "Similar to TIGIT, PVRIG, presented on NK cells and CD8+ T cells, is a suppressible receptor that could identify CD112 on tumor cells." (PMID 37510993, 2023). "This hypothesis is further supported by the correlations we observe between TIGIT+ T cells and CD155+ mAPCs within tumours." (PMID 37596248, 2023). "TIGIT expression was found to be upregulated in various immune cells after MWA, and combining TIGIT blockade with MWA significantly enhanced the expansion and functionality of CD8+ tumor-infiltrating lymphocytes (TILs) and reshaped myeloid cells in the tumor microenvironment." (PMID 37182153, 2023). "Especially TIGIT, which is expressed on tumor-infiltrating cytotoxic T cells in multiple malignancies and its ligand CD155, often expressed by tumor-infiltrating myeloid cells and upregulated on cancer cells, provide a promising target to overcome the local suppression of immune surveillance." (PMID 37449210, 2023). "Notably, we further examined the expression of TIGIT and CD155 on the whole tissue section using immunohistochemical analysis from 32 PDAC samples which contained both tumor tissues and adjacent paracancerous tissues." (PMID 37649613, 2023). "TIGIT interacts with CD155, resulting in a reduced anti-tumor effect." (PMID 37359558, 2023). "Within the subset of tumours where TIGIT-expressing cells do not commonly co-express CD226, this will likely be the dominant mechanism of action." (PMID 37596248, 2023). "On the other hand, CD155 also binds checkpoint inhibitory receptors, including T cell immunoreceptor with Ig and ITIM domains (TIGIT) and T cell-activated increased late expression (Tactile or CD96), thus counteracting DNAM-1 action in the late phases of tumor progression." (PMID 37629138, 2023). "In TIGIT+ Treg cells, the expression level of many immunosuppressing marker genes, including Foxp3, Helios, neuropilin-1, CTLA-4, PD-1 and LAG-3, was upregulated, which inhibited the tumor killing function of T cells." (PMID 38110467, 2023). "Dual blockade of PD-1 and TIGIT has been shown to significantly enhance the expansion and function of tumor antigen-specific CD8+ T cells in vitro and promote tumor regression in mouse tumor models." (PMID 38203670, 2023). "TIGIT is expressed on naïve T cells and activated NK cells and Tregs, and interacts with its two major ligands, poliovirus receptor (PVR; CD155) and poliovirus receptor-related 2 (PVRL2; CD112), which are expressed on myeloid cells and tumour cells." (PMID 37627206, 2023). "As TIGIT is highly expressed in HCC, and is a new immunotherapeutic target that may be regulated by RT, we introduced 125I seed implantation into the tumor for brachytherapy and regulated the expression of TIGIT." (PMID 37124530, 2023). "TIGIT+ Tregs represent a highly active and suppressive phenotype with TIGIT signalling driving this phenotype with suppression of anti-tumour immunity being mediated via these Tregs and not CD8+ T cells." (PMID 37325585, 2023). "Tumor exposure alone or with TIGIT blockade did not change the frequency of NK cells expressing inhibitory receptors TIM-3, NKG2A, LAG-3, PD-1, or CD96 compared to isotype control or unexposed NK cells." (PMID 37345049, 2023). "Antibodies against LAG-3, TIM-3, TIGIT, CD47, and B7-H3 are the most advanced IC blockade drugs and may be approved for the treatment of specific tumor types in the near future, depending on the results of the trials." (PMID 35164813, 2022).
tumor (continued). "In addition, DNAM-1 shares the same ligands of the TIGIT and CD96 inhibitory receptors but exhibits opposite functions with respect to them, suggesting a complementary role in the regulation of tumor immunity and inflammatory response." (PMID 35891197, 2022). "Effector genes such as GZMB, GZMH and KLRG1 were the marker genes in clonotypes shared by all tissues, while the clonotypes present only in tumor showed upregulated T-cell exhaustion genes (HAVCR2, LAG3, CTLA4, TIGIT, PDCD1, and ICOS) and activation genes (SELL and TNFRSF9)." (PMID 36185254, 2022). "The combination of TIGIT blocker and MWA significantly promoted the increase of CD8+ TILs in tumor." (PMID 36002305, 2022). "TIGIT competes with CD226 to bind to PVR (CD155) and Nectin-2 (CD112) two molecules often up-regulated on tumor cells thus playing an important role in the NK-cell activity inhibition in part counterbalanced by the co-stimulatory activity exert by DNAM-1(CD226) receptor." (PMID 36291830, 2022). "In addition, TIGIT inhibits NK cell degranulation, cytokine production and NK cell-mediated cytotoxicity in CD155+ tumor cells." (PMID 36612100, 2022). "Besides, the expression of cell exhaustion-related genes, including PDCD1, CTLA4, LAG3, and TIGIT, was upregulated in several tumors, indicating that UBE2S was intensely involved in tumor evasion via different mechanisms." (PMID 35578600, 2022). "TIGIT has three ligands; (i) CD113, of which the expression is limited to non-hematopoietic tissues, (ii) CD155 and (iii) CD112, mainly expressed on DCs and T cells, and often overexpressed on tumor cells." (PMID 35327475, 2022). "CD226 downregulation could be a barrier to the effective targeting of this axis because it is required for enhancing the anti-tumor CD8+ T cell responses upon PD-1 and TIGIT blockade." (PMID 36544779, 2022). "Compared to tumors treated with combination therapy, the addition of physical activity inhibited the infiltration of immunosuppressive Treg cells and the expression of several immune checkpoints, including CTLA4, TIGIT and TIM3, reprogramming the tumor immune microenvironment." (PMID 35379324, 2022). "TIGIT is a negative checkpoint receptor that is mostly upregulated by NK and T cells, and its ligands are mainly expressed by tumor cells and APCs." (PMID 35078492, 2022). "Moreover, other immune checkpoints, such as TIGIT, LAG-3, and TIM-3, can boost tumour immune evasion and motivate the exhaustion of virus-specific T cells." (PMID 36484006, 2022). "In addition, tumor infiltrating CD8+, CD4+ T cells, and NK cells are often found to express high levels of TIGIT, the interaction of which with CD155 is known to suppress the antitumor effect of these cells." (PMID 36268020, 2022). "Tumor-bearing mice treated with combination therapy showed higher amounts of CD8+ TILs that expressed IFN-γ, Granzyme B, Perforin, TNF-α, TRAIL and FasL than untreated mice, OX or TIGIT mAb alone." (PMID 36389751, 2022). "The main objective of this study was to simultaneously analyze, using flow cytometry, the relative ex vivo expression of five major ICs, namely PD-1, TIGIT, Tim-3, Lag3 and NKG2A, by the CD3+ TILs of CRCs, as well as that of their ligands by the tumor cells and myeloid cells of the TME." (PMID 36077799, 2022). "Tumor cells showed either none or moderate to strong TIGIT expression in a rather cytoplasmatic pattern." (PMID 35410311, 2022). "Nectins are ligands of the inhibitory receptor T-cell immunoreceptor with Ig and ITIM domains (TIGIT), a inhibitory checkpoint receptor, which is expressed on most natural killer cells cells and multiple T cell subsets, including CD8+ tumor infiltrating lymphocytes (TILs)." (PMID 36268557, 2022). "Collectively, these results demonstrated that TIGIT+ T cells have dysfunctional TCR signaling also in SNneg samples without detectable tumor cells." (PMID 34165864, 2022).